CD36 (CD36 molecule (CD36 blood group))
Diseases named in the same sentence as CD36 in open-access papers (continued):
Sharing a sentence is not in itself a finding about the gene and the disease.
type 2 diabetes (continued). "In the type 2 diabetes group, subjects harboring the AA/AG genotype of rs1761667 were fivefold more likely to have CD36 gene methylation than subjects harboring the GG genotype (OR = 5.35 [1.59–17.96], p < 0.01)." (PMID 36031603, 2022). "Subjects with CD36 gene methylation had a significant increase in the DNMT3a level in the control group (p = 0.009) and in the type 2 diabetes group (p = 0.002)." (PMID 36031603, 2022). "LR can improve cardiac diastolic dysfunction in patients with type 2 diabetes by affecting the expression of cardiac FAT/CD36 and converting fatty acids in cardiomyocytes into glucose." (PMID 36619308, 2022). "Four core genes (COL4A2, ACACB, GLUL, and CD36) were found to be highly expressed in subcutaneous adipose tissue of obese patients accompanying type 2 diabetes." (PMID 34085602, 2021). "While PPARγ agonists and most of PPARγ target genes are proven protection in type 2 diabetes and cardiovascular diseases, a minority of PPARγ target genes, such as CD36, are reported to promote VSMC proliferation and tumor metastasis." (PMID 31253783, 2019). "CD36 has since been found to be important in the development of type 2 diabetes and essential hypertension in humans." (PMID 28130354, 2017). "Additionally, several studies associate an increase of soluble form of CD36 (sCD36) in symptomatic carotid stenosis with metabolic disorders, such as type 2 diabetes mellitus (T2DM)." (PMID 27525284, 2016). "Our findings also demonstrated significant association between CD36 gene polymorphism and triglycerides and HDL cholesterol, the traits predisposing to type 2 diabetes." (PMID 23249574, 2012). "Cell culture study on monocyte CD36 expression showed a 34% expression increase in type 2 diabetes as compared with control subjects." (PMID 23249574, 2012). "As such, inhibiting FAT/CD36 cycling in the skeletal muscle of obese type 2 diabetic patients should be sufficient to diminish lipid accumulation." (PMID 22194967, 2011). "As CD36 transcription is regulated by Ppar-γ and its co-receptor and Ppar-γ agonists have already been approved for the treatment of Type 2 diabetes, the authors tested the effect of rosiglitazone on malaria infection." (PMID 20531941, 2010). "We did not observe any particular effect of the combination of CD36 gene polymorphisms and methylation on the circulating sCD36 level in the control group or the type 2 diabetes group." (PMID 36031603, 2022). "A combination of the CD36 polymorphism effect and the CD36 methylation effect did not significantly reduce sCD36 levels in subjects with type 2 diabetes." (PMID 36031603, 2022). "However, for rs3211867, in the type 2 diabetes group, subjects harboring the CC genotype were 13-fold more likely to have CD36 gene methylation than subjects harboring the AA/AC genotype (OR = 12.75 [2.29–70.97], p < 0.01)." (PMID 36031603, 2022). "CD36 gene polymorphisms were not a risk factor for type 2 diabetes (for rs1761667, OR = 0.79 [0.43–1.44] p = 0.9; for rs3211867, OR = 1 [0.56–1.79] p = 0.9)." (PMID 36031603, 2022). "Therefore, the objective of this study was to assess the role of sCD36 in type 2 diabetes and the influence of two common CD36 intronic SNPs, rs1761667 (G/A) and rs3211867 (C/A), and CD36 gene methylation in Senegalese females." (PMID 36031603, 2022). "In addition, sulfo-N-succinimidyl oleate (SSO), a CD36 inhibitor, can improve metabolic disorders and cardiac dysfunction in rats with type 2 diabetes." (PMID 34094645, 2021). "There are several reports suggesting that CD36 may play a role in affecting different disease phenotypes that include Alzheimer’s disease, heart disease, cancer, obesity, type 2 diabetes mellitus (T2DM) and associated metabolic disease." (PMID 30065793, 2018).
type 2 diabetes (continued). "A total of eleven of genes were differently expressed in celiac patients compared with disease controls of which CD36, CD38, FOXP1, SELL, PPARA, PPARG, AGT previously associated with type 2 diabetes and AKAP6, NTNG1 with anorexia nervosa remained significant after correction for multiple testing." (PMID 27483138, 2016). "Thus, even a combination of the effects of CD36 polymorphisms and CD36 methylation did not significantly reduce sCD36 levels in subjects with type 2 diabetes." (PMID 36031603, 2022). "Additionally, the CD36-Fabp4-PPARγ and AMPK-ACC-CPT1 signaling pathways may be related to IR and type 2 diabetes caused by catch-up growth." (PMID 34983495, 2022). "Serum sCD36 levels have been correlated with tissue CD36 expression and are elevated in patients with type 2 diabetes mellitus (T2DM), especially those with lipid-induced renal injury and inflammation, suggesting its potential as a non-invasive biomarker of DKD progression." (PMID 40496556, 2025). "Increased expression of platelet activation markers CD31, CD36, CD49b, CD62P and CD63 was confirmed by Eibl and co-workers when type 2 diabetics were compared with normal individuals." (PMID 27036108, 2016). "We monitored total FAT/CD36 and caveolin 3 expression in Control derived from four different healthy subjects (1 to 4) and in OBT2D derived from three obese type 2 diabetic patients (1 to 3) cells before fractionation." (PMID 22194967, 2011). "For instance, patients with type II diabetes mellitus exhibited the overexpression of various pro-inflammatory M1 polarisation markers [CD16, interleukin-6 (IL-6), iNOS, tumor necrosis factor-α (TNF-α), and CD36] in their PBMCs compared to healthy subjects." (PMID 37375598, 2023). "We found that the allelic frequencies and genotypic distribution of the CD36 gene were not significantly different between the two groups (control and type 2 diabetes)." (PMID 36031603, 2022). "The subjects with type 2 diabetes with CD36 gene methylation had an increase in sCD36 levels and a consequent absence of a significant difference in sCD36 levels compared to subjects with type 2 diabetes without CD36 gene methylation." (PMID 36031603, 2022). "This difference in sCD36 levels according to CD36 gene methylation was not significant in the group with type 2 diabetes." (PMID 36031603, 2022). "Additionally, DM and hyperglycemia are associated with increased expression of oxLDL scavenger receptors CD36, SR-A and LOX-1, and macrophages from type 2 diabetics showed higher uptake of oxLDL." (PMID 30998773, 2019). "In contrast to healthy subjects, most regular consumption trials with patients suffering from type 2 diabetes or impaired glucose tolerance found lower concentrations of ICAM-1 and P-selectin in serum or plasma and a reduced expression of VLA-4, CD36, and CD40 on monocytes." (PMID 27240397, 2016). "Moreover, the DNMT3a level was significantly increased in subjects with CD36 gene methylation compared with subjects without CD36 gene methylation in control subjects (p = 0.009) and in subjects with type 2 diabetes (p = 0.002)." (PMID 36031603, 2022). "CD36 gene methylation was not significantly different between control subjects and subjects with type 2 diabetes, and females with type 2 diabetes did not demonstrate increased levels of CD36 gene methylation (Chi2 = 3.56; RR = 1.46; OR = 2.24 [0.96–5.21] 95% CI; p = 0.10)." (PMID 36031603, 2022). "In addition, we found a nonsignificant increase in sCD36 levels in the type 2 diabetes group with CD36 gene methylation compared to the control group with CD36 gene methylation (p = 0.26)." (PMID 36031603, 2022).
gastric cancer (68 papers, 2019 to 2026). A primary or metastatic malignant neoplasm involving the stomach. "CD36, known for its involvement in fatty acid uptake, has been implicated in promoting gastric cancer metastasis." (PMID 38440405, 2024). "A previously published study has implicated that CD36 promotes metastatic disease in gastric cancer via the Akt/GSK-3β/β-catenin pathway." (PMID 35008415, 2022). "FA supply can increase the O-linked N-acetylglucosamine (O-GlcNAc) modification of CD36 via hexosamine biosynthesis pathway, resulting in an increase of CD36 expression on cell membranes of gastric cancer cells." (PMID 33995128, 2021). "PA uptake by CD36 has been shown to cause AKT phosphorylation in gastric cancer cells and inhibit glycogen synthase kinase 3β (GSK-3)/β-catenin degradation and promote gastric cancer metastasis." (PMID 31410189, 2019). "Furthermore, the heightened expression of CD36 has been linked to unfavorable prognoses in metastatic breast cancer, ovarian cancer, gastric cancer, prostate cancer, and oral squamous cell carcinoma." (PMID 41034734, 2025). "Aoki and Pan found high expression of CD36 may be associated with peritoneal metastasis of gastric cancer." (PMID 36969190, 2023). "Interestingly, the Cys272-Cys333 disulfide bond in CD36 was shown to be cleavable using hydrogen sulfide (H2S), and the loss of this specific motif enhanced FA uptake and metastasis of gastric cancer cells." (PMID 37371076, 2023). "SARIFA-positivity has also been associated with the upregulation of fatty acid metabolism, including the upregulation of FABP4 and CD36 in gastric cancer." (PMID 40055484, 2025). "Specifically, CD36 mRNA expression was down-regulated in gastric cancer tissues compared to normal tissues." (PMID 40061897, 2025). "CD36 showed significantly higher expression in SARIFA-positive gastric cancers (p = 0.0049, Wilcoxon test)." (PMID 41228384, 2025). "By facilitating the uptake of fatty acids, CD36 supports the growth and drug resistance of gastric cancer cells." (PMID 40182050, 2025). "In several tumor types, CD36 is closely associated with EMT, such as gastric cancer, hepatocellular carcinoma and cervix cancer." (PMID 40640171, 2025). "For example, CD36 interacts with TGF-β to promote EMT in cervical cancer, while CD36-mediated fatty-acid metabolism in gastric cancer drives metastasis." (PMID 41550652, 2025). "High expression of CD36 is correlated with poor prognosis in various types of tumors, including breast cancer, ovarian cancer, gastric cancer, and prostate cancer." (PMID 41421797, 2025). "In this RT-qPCR validation, CD36 demonstrated statistically significant variations in mRNA expression levels between gastric cancer tissues and adjacent healthy tissues." (PMID 40061897, 2025). "Fatty acid-induced O-GlcNAcylation promotes the transcription and function of CD36 by directly modifying the S468 and T470 sites of CD36 through activation of the NF-κB pathway, thereby driving gastric cancer metastasis." (PMID 39897929, 2025). "In another study, the authors showed that in gastric cancer, fatty acid induced CD36 expression through O-GlcNAcylation." (PMID 38319449, 2024). "In previous studies, it has been demonstrated that CD36-mediated cancer is associated with AKT pathway activation, as observed in gastric cancer and hepatic carcinoma." (PMID 38319449, 2024). "In gastric cancer, it was proved that FA-induced hyper-O-GlcNAcylation promotes the expression of CD36 by increasing the activity of NF-κB and directly modifying CD36 at S468 and T470,which is convenient for the metastasis of gastric cancer." (PMID 39493763, 2024). "CD36 expression is significantly upregulated in malignant epidermal tumors, such as ovarian cancer, gastric cancer, glioblastoma (GBM), and oral squamous cell carcinoma (OSCC)." (PMID 38276607, 2024). "Hypoxia also induces gastric cancer cells to express CD36, enabling the uptake of free fatty acids, consequently leading to peritoneal metastasis." (PMID 39584783, 2024).
gastric cancer (continued). "In gastric cancer, low concentrations of PA (50 and 100 μM) induced cell migration and invasion through CD36-dependent activation of the AKT pathway, whereas high concentrations of PA reduced cell migration and invasion possibly because of lipotoxicity." (PMID 38786008, 2024). "FA-induced O-GlcNAcylation of CD36 at Ser468 and Thr470, leading to enhanced FA uptake activity of CD36, which drives gastric cancer metastasis." (PMID 39551780, 2024). "The O-GlcNAcylation of CD36 subsequently enhanced cellular FA uptake and promoted metastasis of gastric cancer models." (PMID 37371076, 2023). "Adipose tissue, a favorable site for peritoneal metastasis (PM) from gastric cancer (GC), promotes this process by providing free fatty acids (FFAs); however, the role of CD36 in PM progression from GC remains to be elucidated." (PMID 36042102, 2023). "The pharmacologic inhibition of OGA was recently shown to activate the NF-κB pathway in gastric cancer cells to markedly induce CD36 transcription, as well as increase the O-GlcNAcylation of CD36 protein." (PMID 37371076, 2023). "Here, we established an activated CD4+ memory T cells-related 3-gene prognostic model (BATF2, MYB and CD36) in gastric cancer to evaluate the activation status of CD4+ memory T cells." (PMID 37781029, 2023). "In gastric cancer, palmitate acid (PA) induces cancer cells to upregulate CD36, activating downstream pro-tumor signaling pathways." (PMID 37207149, 2023). "They found that phosphorylating AKT in gastric cancer cells causes glycogen synthase kinase 3 (GSK-3)/-catenin degradation and promotes CD36-regulated gastric cancer metastasis." (PMID 36816174, 2022). "CD36 can also induce EMT in gastric cancer by mediating the uptake of palmitic acid, leading to the upregulation of DEK and activation of the AKT/GSK-3β/β-catenin signaling pathway, resulting in increased migration and invasion of cancer cells." (PMID 36354702, 2022). "Fatty acid translocase (FAT)/CD36, a multifunctional protein that mediates FAs uptake is highly expressed in glioblastoma, oral squamous cell carcinoma, ovarian, and gastric cancer." (PMID 35159223, 2022). "They demonstrated that CD36 promotes migration and invasion in gastric cancer via uptake of exogenous PA and activation of GSK-3β/β-catenin signalling." (PMID 36428985, 2022). "In gastric cancer, CD36 mediates DEK/AKT/GSK-3/β-catenin signaling, and CD36 can act as a direct target molecule for hydrogen sulfide." (PMID 35625633, 2022). "In parallel with previous reports that suggest CD36 promotes invasion and metastasis of ovarian and gastric cancer cells, we found that CD36 promotes colony formation and trans-well invasion of CRC cells in vitro." (PMID 35008415, 2022). "CD36 was found to increase the uptake of exogenous palmitic acid in gastric cancer and induce metastasis via the AKT/GSK-3β/β-catenin signaling pathway." (PMID 35785165, 2022). "CD36 also enhances migration and invasion in gastric cancer cells in vitro as well as local invasion and metastasis in ovarian cancer xenografts." (PMID 35008415, 2022). "Recent studies have shown that high O-GlcNAcylation induced by a high-fat diet promotes transcription and activity of CD36 through activation of the NF-κB pathway and direct modification of CD36 at Ser468 and Thr470, thereby driving gastric cancer metastasis." (PMID 36611964, 2022). "OGA inhibition (Thiamet-G) of gastric cancer cells increased CD36 mRNA and protein levels while Ogt KO or siRNA diminished both basal and PA-stimulated CD36 abundance." (PMID 36111295, 2022). "Upregulation of CD36 leads to increased fat uptake in gastric cancer cells, forming a vicious cycle that promotes gastric cancer metastasis." (PMID 33897888, 2021). "H2S upregulates the expression of the fatty acid receptor CD36 in gastric cancer cells and directly activates CD36, triggering lipid metabolism reprogramming and thereby promoting gastric cancer metastasis." (PMID 33897888, 2021).
gastric cancer (continued). "It has been shown that increased CD36 expression in gastric cancer is correlated with poor prognosis; accordingly, palmitate promotes gastric cancer metastasis in a CD36-dependent manner." (PMID 31847240, 2019). "The increased expression of the FA transporter CD36 in gastric cancer tissues also correlated with poor prognosis in patients." (PMID 31817676, 2019). "This study suggests that hypoxia-induced CD36 expression may be one of the important mechanisms of gastric cancer progression." (PMID 40061897, 2025). "Recent research demonstrated that CD36 could mediate PA-induced metastasis of gastric cancer and initiate the metastasis of OSCC with the stimulation of exogenous PA." (PMID 39875372, 2025). "Monoclonal antibodies against CD36 may reduce abdominal metastasis of gastric cancer, which is the focus of future preclinical research." (PMID 40061897, 2025). "PA enters gastric cancer (GC) cells through its receptor CD36, promoting GC metastasis." (PMID 38276607, 2024). "In gastric cancer, CD36 is a key receptor for PA to induce cancer cell metastasis." (PMID 38319449, 2024). "CXCL3 protein levels in the supernatant of CD36 overexpressed gastric cancer cells also decreased." (PMID 37781029, 2023). "Notably, CD36 overexpression in breast and gastric cancers has been demonstrated to mediate metabolic rewiring to favor FAO, as well as confer metabolic plasticity during nutrient deprivation." (PMID 37371076, 2023). "Interestingly, elevated fatty acid uptake activity promotes the metastatic potential of gastric cancer cells in a CD36-dependent manner via upregulation of O-GlcNAcylation." (PMID 38060103, 2023). "We next co-cultured Jurkat T cells with CD36 overexpressed or knockdowned gastric cancer cells." (PMID 37781029, 2023). "Consequently, the induction of CD36 expression facilitates fatty acid uptake in gastric cancer cells, forming a vicious cycle between O-GlcNAcylation and CD36 transcription." (PMID 38060103, 2023). "In this group, all of the genes except cd36, ghrl, and kit proto-oncogene (kit) displayed overexpression in gastric cancer, which might suggest their oncogenic effect." (PMID 35650297, 2022). "The results of this study suggest that CD36 may serve as a potential therapeutic target for metastatic gastric cancer." (PMID 35785165, 2022). "Moreover, in gastric cancer with peritoneal metastasis (PM), CD36 was shown to promote EMT through PI3K/AKT/mTOR pathway." (PMID 36354702, 2022). "The importance of CD36 in the regulation of proliferation, metastasis, and angiogenesis of different tumor types has been demonstrated, such as oral cancer, cervical cancer, gastric cancer, and leukemia." (PMID 33771982, 2021). "The expression of CD36 was reported in relation to gastric cancer metastasis via O-GlcNAcylation." (PMID 33178362, 2020). "Our previous study showed that O-GlcNAcylation of CD36, a regulator of fatty acid transport, could promote gastric cancer metastasis." (PMID 32863962, 2020). "In gastric cancer, CD36 promotes the uptake of exogenous palmitic acid to induce metastasis via the AKT/GSK-3β/β-catenin signaling pathway; therefore, targeting CD36 might constitute a promising new therapeutical approach for peritoneal metastases." (PMID 33364199, 2020). "Although CD36 expression correlates with an unfavorable prognosis in gastric cancer (GC), its specific contribution to disease onset, progression, and/or metastasis remains unclear." (PMID 33232276, 2020). "CD36 expression was upregulated in gastric cancer cells under hypoxic conditions, and the upregulation of CD36 expression promotes the migratory and invasive ability of GC cells and peritoneal tumor growth using exogenous FFA." (PMID 38276607, 2024). "Also, CD36 is a key mediator of exogenous FA-induced gastric cancer metastasis." (PMID 37612265, 2023). "However, gastric cancer cells also have up-regulated CD36 and lipid metabolism." (PMID 36969190, 2023).